CREB5 (cAMP responsive element binding protein 5)
Diseases named in the same sentence as CREB5 in open-access papers (continued):
Sharing a sentence is not in itself a finding about the gene and the disease.
metabolic syndrome (2 papers, 2009 to 2019). A cluster of metabolic risk factors for CARDIOVASCULAR DISEASES and TYPE 2 DIABETES MELLITUS. "CREB5 was more expressed in omental adipose tissue biopsies of women with metabolic syndrome than in those of healthy women." (PMID 19689798, 2009). "Finally, eleven CpG sites were associated with metabolic syndrome: cg08862778 (MTOR), cg11322849 (INS), cg07199894 (ULK1), cg11658986-cg04149773 (ADCY6), cg14862787-11301281 (CREB5), cg14844401-cg20300093 (ADCY5), cg01284192 (IGF1R) and cg08128650 (RELA)." (PMID 30926763, 2019). "In liver biopsies, two CpG sites (cg15283498-FOXO3; cg07012178-PRKAG2) were hypomethylated, whereas in subcutaneous adipose tissue from subjects with or without metabolic syndrome, cg07340599 (CREB5) and cg08779982 (TSC2) were hypomethylated." (PMID 30926763, 2019).
alcoholism (1 paper, 2019). "(Alcoholism, amphetamine addiction, cocaine addiction) ATF2, CREB1, CREB5, and FOSB in all three substance disease KEGG pathways are suspected be related with CREB and FOS family, and JUN." (PMID 30899073, 2019). "Moreover, ATF2, CREB1, CREB5, and FOSB in all three substance diseases (alcoholism, amphetamine, and cocaine addiction pathways)." (PMID 30899073, 2019).
Arthritis (1 paper, 2022). Inflammation of a joint. "CREB5 was also found as a transcription factor to regulate prg4 expression and prevent arthritis." (PMID 35773668, 2022).
carcinoid (1 paper, 2014). "We also evaluated the expression data of CREB5, PTPRB and COL4A3 from Oncomine, indicating that CREB5, PTPRB and COL4A3 were significantly lower in carcinoid than normal lung tissues, which was accordant to the results of the DASL and RNA-seq datasets." (PMID 25105010, 2014).
chondrosarcoma (1 paper, 2021). A malignant cartilaginous matrix-producing mesenchymal neoplasm arising from the bone and soft tissue. "To begin to determine whether Creb5 can confer competence for Prg4 expression in growth plate-like chondrocytes, we infected either a human chondrosarcoma cell line (SW1353) or an immortalized human costal chondrocyte cell line (C-28/I2;49) with lentivirus encoding either EGFP or Creb5." (PMID 33712729, 2021).
chordoma (1 paper, 2008). Chordomas are rare malignant tumors arising from embryonic remnants of the notochord in axial skeleton. "This region harbours the genes CREB5, CPVL, and CHN2, none of which has any obvious role in chordoma development." (PMID 18071362, 2008).
Cirrhosis (1 paper, 2025). A chronic disorder of the liver in which liver tissue becomes scarred and is partially replaced by regenerative nodules and fibrotic tissue resulting in loss of liver function. "We also explored the relationship between CREB5 expression and the clinicopathological features of HCC, finding that high CREB5 expression was correlated with tumor size and degree of differentiation, but not with age, sex, history of hepatitis/cirrhosis, or AFP level." (PMID 39915455, 2025).
Cognitive impairment (1 paper, 2025). Abnormal cognition is characterized by deficits in thinking, reasoning, or remembering. "Furthermore, modulation of the miR‐32533/CREB5 axis ameliorated or worsened cognitive impairment by inhibiting or amplifying Aβ overproduction through the BACE1‐involved amyloidogenic and ADAM10‐involved non‐amyloidogenic pathways." (PMID 39840513, 2025). "Our findings indicate that the novel miR‐32533/CREB5 signaling may serve as a potential therapeutic target for ameliorating Aβ‐elicited cognitive impairment by reducing Aβ production, oxidative stress, and neuroinflammation in AD." (PMID 39840513, 2025).
diabetic angiopathies (1 paper, 2022). "Our results indicated that Nar exerted anti-proliferation and anti-migration effects on high-glucose-induced VSMCs through decreasing expression of the target protein VEGFA, and then downregulating the PI3K/Akt/CREB5 pathway, suggesting its potential for treating diabetic angiopathies." (PMID 35754483, 2022).
eosinophilia (1 paper, 2022). "The histological analysis found that inhibiting Creb5 resulted in a profound decrease in mucus-secreting cells and lung eosinophilia, and presented with a significantly reduced inflammatory score." (PMID 36038770, 2022).
glioblastoma (1 paper, 2024). The most malignant astrocytic tumor (WHO grade IV). "In this study, we demonstrate the role of CREB5 in glioblastoma, particularly in GSCs." (PMID 38418476, 2024).
Graves disease (1 paper, 2020). Graves' disease is an autoimmune disorder that leads to overactivity of the thyroid gland (hyperthyroidism).It is caused by an abnormal immune system response that causes the thyroid gland to produce too much thyroid hormones. "The methylation altered in these genes may affect tumor proliferation; for instance, the CREB5 continuously decreased in mCG was hypomethylated in Graves’ disease." (PMID 32258002, 2020).
Hyperglycemia (1 paper, 2023). An increased concentration of glucose in the blood. "In the present study, we observed that high glucose is not able to induce FXR and CREB5 in HK2 cells in contrast with AGEs and PA, suggesting that hyperglycemia, AGEs, and fatty acids have distinct impacts on kidney cells in early DN." (PMID 37337149, 2023).
hypertensive diseases (1 paper, 2021). "In our GWAS, genes related to blood pressure (NLRP6, CREB5 and APOE) were found in regions associated with mtDNA abundance, providing a potential explanation between increased mtDNA abundance and reduced risk for hypertensive diseases." (PMID 33385171, 2021).
influenza (1 paper, 2013). An acute viral infection of the respiratory tract, occurring in isolated cases, in epidemics, or in pandemics; it is caused by serologically different strains of viruses (influenzaviruses) designated A, B, and C, has a 3-day incubation period, and usually lasts for 3 to 10 days. "CREB5 was not at all highly ranked in influenza network topology measures, however its differential expression profile exhibited down-regulation in HP virus, and up-regulation in LP strains (not shown)." (PMID 23935999, 2013).
leukemia (1 paper, 2024). A malignant (clonal) hematologic disorder, involving hematopoietic stem cells and characterized by the presence of primitive or atypical myeloid or lymphoid cells in the bone marrow and the blood. "One possible explanation for this contradiction is that the growth dependency on CREB5 has been abolished in JIH5 by additional gene abnormalities acquired during the leukemia development or transformation of primary leukemia cells to the cell line." (PMID 39015025, 2024). "The contribution of CREB5 to leukemia cell growth should be investigated using primary Z‐fusion (+) ALL cells." (PMID 39015025, 2024).
melanoma (1 paper, 2020). A malignant, usually aggressive tumor composed of atypical, neoplastic melanocytes. "Along with FOXD1 and ATF3, CREB5 formed a transcription factor regulatory network that negatively regulates MAPK signalling, which is suppressed by FZD3 in melanoma." (PMID 32843066, 2020).
meningioma (1 paper, 2012). A generally slow growing tumor attached to the dura mater. "With respect to downstream gene sets of PI3K/Akt pathway, proliferation-promoted genes such as CTNNB1, CREB1, CREB5, and TCF7L2 were up-regulated in fibroblastic meningioma." (PMID 23285163, 2012).
migraine (1 paper, 2021). "We identified common targets associated with migraine and the hsa‐miR‐155‐5p high confidence target space such as PLP1, TRAK1, SYNJ1, and CREB5." (PMID 34486248, 2021).
Myeloma (1 paper, 2024). "Additionally, the most activated TFs in each subgroup within the M1-M5 modules were identified as follows: MAF in the C0 IGLL5+ Myeloma Cells subgroup, LEF1 in the C1 IGHG4+ Myeloma Cells subgroup, TCF12 in the C2 MALAT1+ Myeloma Cells subgroup, and CREB5 in the C3 IGHG1+ Myeloma Cells subgroup." (PMID 39281682, 2024).
nasopharyngeal carcinoma (1 paper, 2013). A carcinoma arising from the nasopharyngeal epithelium. "The relationships among EBV, CREB5, and 17q22 in nasopharyngeal cancer are therefore well worth further investigation." (PMID 24376627, 2013).
Obesity (1 paper, 2022). Accumulation of substantial excess body fat. "However, there were some differences in DCM from obesity—MBD6, CREB5, and PDE3B were down-regulated and the others were up-regulated." (PMID 36547458, 2022).
osteoarthritis (1 paper, 2023). A noninflammatory degenerative joint disease occurring chiefly in older persons, characterized by degeneration of the articular cartilage, hypertrophy of bone at the margins and changes in the synovial membrane. "For clinical relevance, we extended our analysis to published data from knee synovial tissues of osteoarthritis patients, 28 29 which similarly showed that THY1-PRG4+CLIC5+ FLS exhibited SOX5, FOXO1 and CREB5 regulon activity." (PMID 36414376, 2023).
renal fibrosis (1 paper, 2023). A final common manifestation of a wide variety of chronic kidney diseases characterized by glomerulosclerosis and tubulointerstitial fibrosis. "A recent study showed that CREB lncRNA targeted CREB5 to regulate FN1 in renal fibrosis." (PMID 37176063, 2023).
sarcoma (1 paper, 2025). A usually aggressive malignant neoplasm of the soft tissue or bone. "Several of the FET-sarcoma-specific and shared transcription factors formed a protein interaction network, with MLS-specific JUN, RUNX1, FOSL2, and CREB5 as center nodes." (PMID 40988026, 2025).
Sepsis (1 paper, 2025). Sepsis is defined as life-threatening organ dysfunction caused by a dysregulated host response to infection. "The RT-qPCR results showed the expression of MYO10, SULT1B1, MKI67, and CREB5 had significant differences between controls and sepsis samples (P < 0.05)." (PMID 41246299, 2025). "This study identified 4 biomarkers, namely MYO10, SULT1B1, MKI67, and CREB5 and explored the pathogenesis of sepsis, providing new insights for potential treatment strategies by integrating transcriptomic data and single-cell analysis." (PMID 41246299, 2025). "This study obtained a total of 4 biomarkers (MYO10, SULT1B1, MKI67, and CREB5), and the analysis of nomogram showed that the biomarkers had good clinical predictive value to sepsis." (PMID 41246299, 2025). "Future studies should further clarify the downstream gene network of CREB5 to further reveal its specific mechanism in sepsis." (PMID 41246299, 2025). "This study found that CREB5 was significantly upregulated in sepsis, and was specifically enriched in CD16+ and CD14+ monocytes, and its expression level showed dynamic changes with cell differentiation." (PMID 41246299, 2025). "In the future, further exploration is needed into the specific molecular mechanisms of CREB5 in sepsis and its clinical significance." (PMID 41246299, 2025). "The potential mechanisms of the four biomarkers (MYO10, SULT1B1, MKI67, CREB5) identified in this study in sepsis can be preliminarily interpreted through their known functions and related pathways." (PMID 41246299, 2025). "Additionally, evaluating the efficacy of small-molecule inhibitors targeting CREB5 or MYO10 in sepsis models may provide a theoretical basis for developing novel therapies targeting immune metabolism or cell cycle regulation." (PMID 41246299, 2025). "In the early stage of sepsis, the upregulation of CREB5 may enhance the transcriptional activity of inflammatory factors such as IL-6 and TNF-α by directly binding to the promoter region of inflammatory factors, thus driving the inflammatory response of CD16+ monocytes." (PMID 41246299, 2025). "Furthermore, the functions of CREB5 in cell proliferation and survival, as well as its identified role in immunotherapy resistance, also suggest that it may have a potential role in sepsis-related cell damage repair and immunosuppressive processes." (PMID 41246299, 2025). "CREB5, a key transcription factor of the cAMP-signaling pathway, plays an important role in the initiation and progression of multiple cancers.Although direct research on CREB5 in sepsis is currently limited, existing evidence suggests that it may be involved in immunomodulatory processes." (PMID 41246299, 2025). "In summary, these biomarkers may be involved in sepsis through mechanisms related to cell cycle regulation (MYO10, MKI67), metabolic reprogramming (SULT1B1), and inflammatory signal transduction (CREB5)." (PMID 41246299, 2025). "Secondary clustering and pseudotime analysis of monocytes showed that CREB5 and SULT1B1 tended to be stable in their five differentiation states after significant downregulation in early differentiation, suggesting that they may be involved in the progression of sepsis." (PMID 41246299, 2025).
tendinitis (1 paper, 2024). Inflammation of a tendon, usually resulting from an overuse injury. "The identification of key transcription factors, such as SP110 and CREB5, involved in the regulation of inflammasome genes, provides new insights into the transcriptional control mechanisms in tendinitis." (PMID 38919626, 2024). "Transcription factors like SP110 and CREB5 emerged as key regulators of inflammasome genes, providing insight into the transcriptional control mechanisms in tendinitis." (PMID 38919626, 2024). "Additionally, our study highlights key molecular pathways, immune cells, and transcription factors involved in tendinitis, such as the roles of MYD88, CD36, CREB5, and ELF4." (PMID 38919626, 2024).
toxoplasmosis (1 paper, 2022). A parasitic disease contracted by the ingestion or fetal transmission of toxoplasma gondii. "In addition, the TNF-signaling (bta04668; TRAF5/CREB5/CASP7/CHUK) and the toxoplasmosis (bta05145; TGFβ2/CHUK/CIITA/SOCS1) pathways were significantly enriched." (PMID 35464478, 2022).
viral hepatitis (1 paper, 2021). An acute or chronic inflammation of the liver parenchyma caused by viruses. "Transcriptome profiling revealed that HRH2 and CREB5 expression were increased in viral hepatitis and NASH, confirming involvement of the pathway in disease progression across the major etiologies." (PMID 34535664, 2021).
ZIKV infection (1 paper, 2017). "Further examination of the roles of metabolic control genes such as TERT, ALDH7A1, CREB5, EAPP, and NDUFA11 as they relate to ZIKV infection may provide further insights into ZIKV pathogenesis." (PMID 28442752, 2017).
tumor (30 papers, 2012 to 2026). "Our discovery is consistent with studies demonstrating that CREB5 overexpression in parenchymal cells is associated with clinical tumor recurrence, metastasis, poor prognosis, and overall survival." (PMID 34535664, 2021). "In AR-positive cells, CREB5 overexpression promoted cell colony growth with tumorigenic properties and increased tumor size in vivo." (PMID 41954995, 2026). "Altered expression of EPHA3 also correlates with tumor diseases, which is also true for the potential oncogene CREB5." (PMID 40699665, 2025). "In vivo experiments showed that the tumor size and weight were significantly greater in mice that overexpressed CREB5 than those in the vector group." (PMID 39915455, 2025). "Gene set enrichment analysis (GSEA) revealed significant enrichment of tumor-related genes in the CREB5 high-expression group (NES = 2.20, p.adj < 0.001)." (PMID 39915455, 2025). "Animal experiments showed that CREB5 knockdown significantly reduced tumor weight and volume in a subcutaneous xenograft model using Hep3B cells." (PMID 39915455, 2025). "CREB5, a member of the cAMP response element-binding (CREB) protein family, has been implicated in tumor proliferation, migration, and invasion." (PMID 41145436, 2025). "Several studies have shown the diverse roles of CREB5, especially its involvement in tumor progression in various cancers." (PMID 38418476, 2024). "We found that the knockdown of CREB5 in GSCs inhibited its proliferation and self-renewal activity in vitro and tumor forming ability in vivo." (PMID 38418476, 2024). "For instance, it has been found that increased CREB5 expression is positively correlated with tumor cell invasion and a poor prognosis for cancer patients with epithelial ovarian cancer and hepatocellular carcinoma." (PMID 38418476, 2024). "For example, lncSNHG5 works as a ceRNA by binding with miR-26a-5p, miR-132-3p or miR-154-5p to increase PCNA, GSK3β and CREB5 expression to drive cell proliferation, migration and metastasis of tumor cells 39-41." (PMID 36438499, 2022). "High CREB5 expression was significantly correlated with larger tumor size (diameter greater than 4 cm) and advanced TNM (Tumor Node Metastasis) stage." (PMID 35773668, 2022). "Expression of the downstream effector CREB5 was also associated with poorer overall survival and higher incidence of HCC recurrence after curative tumor resection." (PMID 34535664, 2021). "The COX proportional hazard model demonstrated that doubled expressions of three genes, i.e., CREB5, PTPRB and COL4A3, was associated with 63% to 97% decreased risk of death, recurrence or progression, suggesting their potential role as tumor suppressors." (PMID 25105010, 2014). "According to TCGA datasets, CREB5 was highly expressed in various tumor tissues." (PMID 39915455, 2025). "Additionally, gene silencing by short hairpin RNA (shRNA) of CREB5 has prevented the proliferation and self-renewal ability of GSCs in vitro and decreased their tumor forming ability in vivo." (PMID 38418476, 2024). "More specifically, CREB5 has been found to be overexpressed in many tumor types, including hepatocarcinoma, suggesting it is an independent prognostic factor that could be used when considered treatment strategies." (PMID 39858580, 2024). "The positive correlation between SNHG4 and CREB5 were detected in HCC tumor tissues we collected." (PMID 36565037, 2023). "Furthermore, we found that several upregulated genes in those enhanced subclones, including SYT14, CREB5, and ABCA1, were associated with drug resistance and tumor proliferation in previous reports." (PMID 37324492, 2023). "Hence, we concluded that upregulation of CREB5 promoted tumor progression and inhibited mitochondrial apoptosis in HNSCC." (PMID 35773668, 2022). "In addition, the results of subcutaneous tumor-bearing experiments in nude mice indicate that treatments targeting CREB5 or TOP1MT have a therapeutic effect on HNSCC." (PMID 35773668, 2022).